NGF (nerve growth factor)
Diseases named in the same sentence as NGF in open-access papers (continued):
Sharing a sentence is not in itself a finding about the gene and the disease.
ovarian carcinoma (continued). "Together, these results indicated that NGF/NGFRs can regulate the migration behavior of ovarian cancer cells, relating to cell types and growth conditions." (PMID 27835587, 2016). "In our cell models, NGF and NGFRs were found to be expressed in ovarian cancer cells simultaneously." (PMID 27835587, 2016). "In the future, studies should focus on NGF levels on ovarian cancer patients, and its correlation with prognosis." (PMID 25296882, 2014). "The expression of VEGF, proliferation and the angiogenesis process in ovarian cancer is importantly induced by NGF, among other molecules." (PMID 25296882, 2014). "These growth factors/receptors are present in ovarian cancer cells, so it is possible that survivin could be regulated by growth factors other than NGF, especially in a compensatory manner when NGF is inhibited." (PMID 31817839, 2019). "This factor increases when ovarian cancer cells are stimulated with NGF." (PMID 28245631, 2017). "In this study, we investigated the expression of NGF/NGFRs and β-catenin in ovarian cancer cells." (PMID 27835587, 2016). "Variable levels of NGFRs and endogenous NGF were observed in the four ovarian cancer cells." (PMID 27835587, 2016). "Taken together, these findings demonstrated that NGF may affect the expression or activity of β-catenin by regulating the expression levels of BCL9-2 in ovarian cancer cells." (PMID 27835587, 2016). "Ovarian cancer cells were cultured for 24 hour by serum deprivation, and then were incubated for 24 hour with 100 ng/ml NGF, 10 uM Ro 08-2750+100 ng/ml NGF, 100 uM K252a+100 ng/ml NGF, 5 nM LM11A-31+ 100 ng/ml NGF, and 100 uM K252a+5 nM LM11A-31+100 ng/ml NGF." (PMID 27835587, 2016). "It is important to highlight that EGF and NGF are overexpressed in ovarian cancer." (PMID 26091707, 2016). "Altogether, the results presented here show that NGF may function as a mediator of ovarian cancer cell growth and migration by modulating canonical WNT/β-catenin signaling pathway." (PMID 27835587, 2016). "The emerging data have shown that NGF/NGFRs are overexpressed in ovarian cancer tissues and cells, but very low levels in normal ovarian tissues, which are correlated with the initiation, progression and prognosis of human ovarian cancers." (PMID 27835587, 2016). "The differential expression levels of NGF/NGFRs in ovarian cancer cells suggest that they may have some functional roles in the occurrence and progression in ovarian cancer." (PMID 27835587, 2016). "Our results confirmed that NGF may affect the expression or activity of β-catenin by regulating the expression levels of BCL9-2 in ovarian cancer cells." (PMID 27835587, 2016). "Targeting the NGF-TRKA pathway could offer new approaches to the therapy of ovarian cancer, and it could be complementary to therapies that target VEGF." (PMID 25296882, 2014). "Similar link between NGF and angiogenesis has also been suggested in ovarian carcinomas." (PMID 20569463, 2010). "In addition, NGF may participate in the pathogenesis of polycystic ovary syndrome and ovarian cancer as shown by studies in rodents and humans." (PMID 36032306, 2022). "The expression levels of NGF and its receptor TrkA in ovarian cancer and cervical squamous cell carcinoma are significantly increased and related to the proliferation and metastasis of ovarian cancer as well as the clinical grade and nerve infiltration of cervical cancer." (PMID 34307378, 2021). "NGF may also exert a stimulatory effect in ovarian cancer and polycystic ovarian syndrome." (PMID 32685448, 2020). "In ovarian cancer, it has been demonstrated that growth factors such as EGF may induce the production of H2O2, while in other cell types, it has also been observed that NGF can cause an increase in H2O2 production." (PMID 26091707, 2016).
ovarian carcinoma (continued). "NGF is able to stimulate the cellular proliferation of human ovarian cancer cells, participates in pathological angiogenic processes of ovarian cancer directly or indirectly that may contribute to the growth, aggressiveness and low survival rates for ovarian cancer patients." (PMID 27835587, 2016). "NGF/NGFRs complex can stimulate cellular proliferation of human ovarian cancer cells and participate in extracellular-matrix remodeling, formation of novel blood-vessels, pathological angiogenic processes and so on that affect the migratory behavior of ovarian cancer cells." (PMID 27835587, 2016). "In this report, we found that NGF/NGFRs and β-catenin were coexpression in ovarian cancer cell lines, and NGF can decrease the expression level of β-catenin and affect its activities, which may be related to the NGF-induced down-regulation of B-cell CLL/lymphoma 9-like (BCL9L, BCL9-2)." (PMID 27835587, 2016). "Nerve growth factor (NGF) and its high-affinity receptor TRKA are overexpressed in epithelial ovarian cancer (EOC) displaying a crucial role in the disease progression." (PMID 35216240, 2022). "Epithelial ovarian cancer (EOC) is a lethal gynecological neoplasia characterized by extensive angiogenesis and overexpression of nerve growth factor (NGF)." (PMID 31817839, 2019). "NGF and TRKA overexpression has been found in several cancer types, including thyroid, lung, esophagus, prostate, breast and ovarian cancer." (PMID 28245631, 2017). "In line with this, both NGF and TRKA have been involved in the angiogenesis of EOC through VEGF induction, whose production is the main component of angiogenesis in ovarian cancer." (PMID 28245631, 2017). "Both NGF/NGFRs and WNT/β-catenin signaling pathways are critical for the initiation, development, progression and prognosis of the patients with ovarian cancer." (PMID 27835587, 2016). "The inhibitors of NGF/NGFRs, such as Ro 08-2750, K252a and LM11A-31,can all block NGF-stimulated changes of gene expression or migratory behavior on ovarian cancer cells." (PMID 27835587, 2016). "Some specific antagonists, such as Ro 08-2750 (to NGF), K252a (to TrkA) or LM11A-31 (to P75), can all increase β-catenin expression by inhibiting the roles of NGF/NGFRs in ovarian cancer cells." (PMID 27835587, 2016). "And therefore, there lies some new therapeutic opportunities that anchoring to the interaction between NGF signaling and WNT/β-catenin pathway in ovarian cancer." (PMID 27835587, 2016). "This review will focus on our research efforts regarding the connection between NGF, TRKA and VEGF, and how these molecules have a relevant role in ovarian cancer progression." (PMID 25296882, 2014). "In human epithelial ovarian cancer (EOC) cells, NGF and TRKA are also expressed, and the active form of TRKA has been associated with poor patient outcome." (PMID 25296882, 2014). "NGF has been described to increase the expression of VEGF in various tissues and cells such as ischemic hindlimb, nervous system, epithelial ovarian cancer cells and endothelial cells." (PMID 20569463, 2010). "It has been described that NGF can stimulate the expression of VEGF in several types of cells including endothelial cells, as well as epithelial ovarian cancer cells." (PMID 20569463, 2010). "Several inhibitors of NGF and NGF receptors, such as Ro 08-2750 (targets NGF), K252a (targets TrkA) and LM11A-31 (targets P75), have been shown to increase β-catenin expression and cell migration in ovarian cancer cells." (PMID 33466728, 2021). "In addition, one of the most studied angiogenic factors in ovarian cancer is vascular endothelial growth factor (VEGF), whose expression is increased by NGF/TRKA in EOC cells." (PMID 33081171, 2020). "Importantly, metformin blocks the NGF-induced increase in c-MYC, survivin and VEGF, as well as the increase in MYC and β-catenin/TCF-Lef transcriptional activity in ovarian cancer cells." (PMID 33081077, 2020).
ovarian carcinoma (continued). "The miR-145 and miR-23b are two oncosuppressor miRs that are known to be downregulated in ovarian cancer tissues and in-silico analysis revealed that c-MYC and VEGF could be targets for these miRs, which in turn are modulated by NGF/TRKA." (PMID 33081077, 2020). "However, there are few studies to document the relationship and exact molecular mechanism between NGF signaling and WNT/β-catenin signaling, two important molecular signaling pathways, in modulating the invasion and migration of ovarian cancer cells." (PMID 27835587, 2016). "Our results showed that NGF can down-regulate the expression intensity of β-catenin in ovarian cancer cells, but the regulation mechanism were not known." (PMID 27835587, 2016). "In the present study, we investigated the effect of 0, 5, 10, 20 and 40 uM NGF-related inhibitor Ro 08-2750; 0, 10, 100, 200 and 300 uM TrkA-related inhibitor K252a; and 0, 5, 10, 30 and 100 nM P75-related inhibitor LM11A-31 on the gene expression changes of β-catenin in ovarian cancer cells." (PMID 27835587, 2016). "Endogenous NGF was found lower expression in A2780 and SKOV3 cells, and higher expression was shown in OVCAR3 and CAOV3, which suggested that NGF may regulate the biological behaviors of ovarian cancer cells through an autocrine loop." (PMID 27835587, 2016).
astrocytoma (20 papers, 2007 to 2025). "Corallocin A and C were able to upregulate nerve growth factor (NGF) expression in astrocytoma cells and neurite outgrowth in PC12 cells." (PMID 38892137, 2024). "The compound scabronine A was found to enhance the gene expression of NGF and stimulate the secretion of NGF in 1321N1 human astrocytoma cells." (PMID 38835656, 2024). "H. erinaceus increases nerve growth factor (NGF) protein expression through the JNK pathway in 1321N1 human astrocytoma cells." (PMID 36675019, 2023). "It was demonstrated that the expression level of the nerve growth factor (NGF) gene, secretion of NGF protein, and neurite outgrowth in 1321N1 human astrocytoma cells treated with ethanol extracts of H. erinaceum were all enhanced." (PMID 37375662, 2023). "U373, the astrocytoma cell line used as an experimental model of human astrocytes, retains the potential to fully respond to NGF, as it expresses appreciable levels of both TrkA and p75NTR." (PMID 35563230, 2022). "SG-ME enhanced the secretion of the neurotrophic factor NGF from 1321N1 human astrocytoma cells which was accompanied by the activation of PKC-ζ." (PMID 33281604, 2020). "Nevertheless, these findings substantiate that erinacine C induces ngf expression in 1321N1 astrocytoma cells with NGF accumulating in the supernatant and subsequently eliciting PC12 differentiation via binding and activating TrkA." (PMID 33066380, 2020). "It was shown that the astrocytoma cell line U87 expressed and released increased amounts of NGF in response to 50 pg/ml of exogenous TNFα." (PMID 25841889, 2015). "PRP and NP stimulate human astrocytoma cell line U87 to release the significant amounts of NGF to the extracellular space both in its precursor and mature form." (PMID 25841889, 2015). "Results obtained from ELISA demonstrated that the concentration of the total NGF released by PRP/NP-treated U87 astrocytoma cells was higher than in control cells." (PMID 25841889, 2015). "In conclusion, our observations have shown that the proline-rich polypeptide complex PRP and its nonapeptide fragment NP up-regulate neurotrophic activity of astrocytoma cell line U87 by increase of NGF synthesis and its release into the extracellular space." (PMID 25841889, 2015). "Our results obtained with the human astrocytoma cell line U87 show the effective induction of NGF and IL-6 by PRP/NP." (PMID 25841889, 2015). "It was shown that both PRP and NP at a dose of 10 μg/ml, as well as TNFα (50 pg/ml) used as a reference sample stimulate human astrocytoma cell line U87 to release significant amounts of NGF." (PMID 25841889, 2015). "Using cDNA synthesis and quantitative RT-PCR analysis, human astrocytoma 1321N1 cells treated with triterpenoids were found to upregulate the expression of genes for neurotrophins, including nerve growth factor, as well as brain-derived neurotrophic factor—genes known to regulate neuroprotection." (PMID 36362380, 2022). "Importantly, LGG cell lines generated from distinct primary pediatric astrocytomas showed different proliferative potential in vitro, along with divergent behaviors in response to NGF treatment in terms of proliferation and wound healing delay." (PMID 34257579, 2021). "This is in line with the in vitro finding that ethanolic extract from the fruiting body of H. erinaceus could promote neurite outgrowth in PC12 cells and stimulate NGF synthesis in 1321N1 human astrocytoma cells." (PMID 31881712, 2019). "Thus, erinacine C induced neurotrophic activity secreted from 1321N1 astrocytoma cells—like recombinant NGF—mediates the differentiation of PC12 cells by likely activating PLCγ, PI3K, and MAPK a pattern of intracellular signaling characteristic for neurotrophin-stimulated Trk receptors." (PMID 33066380, 2020).
astrocytoma (continued). "Genes that show higher expression in astrocytoma compared to glioblastoma were CX3CL1, CSF1 (MCSF), CCL3 (MIP1α), CCL4 (MIP1β), TGFα, FLT3LG, CXCL5, CCL19 while KITLG (SCF) and NGF were equally expressed in the two tumor types." (PMID 35301393, 2022). "Among these compounds, erinacine C appeared particularly interesting as this substance was able to induce both Nerve Growth Factor β (NGF) and Brain-Derived Neurotrophic Factor (BDNF) expression in the astrocytoma cell line 1321N1." (PMID 33066380, 2020). "CA enhances the expression of nerve growth factor (NGF) and antioxidant genes, such as HO-1 in an Nrf2-dependent manner in U373MG human astrocytoma cells." (PMID 30959808, 2019). "NGF was shown previously also to induce upregulation of VGSC expression/activity in PC12 cells, frog sympathetic B neurons, human astrocytoma cell lines (1321N1 and A172) and rat PCa Mat-LyLu cells." (PMID 18036246, 2007). "Expression of NGF and BDNF has been found in samples of human astrocytoma." (PMID 32906676, 2020). "NGF expression was reported to be increased, whereas BDNF expression was reduced, both in tumor samples and cerebrospinal fluid (CSF), in children with low-grade astrocytomas and ependymomas." (PMID 32906676, 2020). "However, hericenones failed to promote NGF gene expression in 1321N1 human astrocytoma cells while erinacine A successfully upregulated the NGF level in the locus coeruleus and hippocampus of rats." (PMID 32581767, 2020). "The absence of p75NTR neurotrophin receptor in astrocytomas included in this study erases the possibility of apoptosis mediated by binding of pro-neurotrophins (pro-NGF and/or pro-BDNF) to p75NTR, even in the presence of survival-promoting Trk receptors, in these tumors." (PMID 17971243, 2007). "Although hericenones C and D from the fruiting body of H. erinaceus have shown to induce neuroprotective properties in rats by stimulating NGF synthesis via activation of the c-jun N-terminal kinase (JNK) pathway, they failed to promote NGF gene expression in 1321N1 human astrocytoma cells." (PMID 32581767, 2020).
glioblastoma (20 papers, 2006 to 2025). The most malignant astrocytic tumor (WHO grade IV). "The NGF is expressed in glioblastoma multiforme (GBM), the most common primary malignant brain tumor in adults, and has been shown to stimulate GBM cells." (PMID 38791953, 2024). "SORCS3 is a member of the vacuolar protein sorting 10 protein (VPS10p) receptor family and uses the NGF/p75NTR pathway in glioblastoma (GBM) to suppress cell invasion and proliferation." (PMID 37554401, 2023). "Nrf2 was reported to regulate NGF mRNA expression in glioblastoma cells and normal human astrocytes." (PMID 25974036, 2015). "In a first approach, we studied NGF mRNA expression in the human glioblastoma cell line T98G." (PMID 16594997, 2006). "Using neuronal (NGF‐differentiated PC12) and glial cell (C6 glioblastoma) models, we studied how Aβ1–42‐oligomers affect PB‐associated mRNAs." (PMID 41388939, 2025). "Interestingly, it has been reported that nerve growth factor (NGF), a proteinaceous neurotrophic molecule essential for the growth and functional maintenance of nervous system tissue, was markedly enhanced in T98G human glioblastoma cells following treatment with CA." (PMID 36903551, 2023). "In glioblastoma, PDGFR, NGF, IGF-1 and, most essentially EGFR upregulation, mediates the migration of glioblastoma cells into normal brain tissues." (PMID 32276377, 2020). "In previous work, we demonstrated that CA induces NGF gene expression in an Nrf2-dependent manner in T98G and U373MG human glioblastoma cells." (PMID 30959808, 2019). "A subsequent dose-response analysis revealed that CA remarkably induced NGF in U373MG cells at a high-dose (50 μM), which is reminiscent of our previous observation in T98G glioblastoma cells." (PMID 30959808, 2019). "Finally, carnosine has also been shown to stimulate the secretion of neurotrophins such as Brain-Derived Neurotrophic Factor (BDNF) and Nerve Growth Factor (NGF) in human glioblastoma-derived U-87 MG cells, but not in neuronal SH-SY5Y cells, suggesting a cell type-specific mechanism of action." (PMID 41527663, 2025). "However, inhibiting PLCγ disrupts the invasion of glioblastoma cells into normal brain tissues, regardless of the combined signaling effects of PDGFR, NGF, IGF-1, and EGFR upregulation." (PMID 32276377, 2020).